RHOC (ras homolog family member C)
Diseases named in the same sentence as RHOC in open-access papers (continued):
Sharing a sentence is not in itself a finding about the gene and the disease.
breast carcinoma (continued). "Moreover, ATOH8-V1 directly binds to the RhoC promoter and stimulates the expression of RhoC, which in turn enhances the metastasis of breast cancer." (PMID 33049034, 2021). "RHOC has been shown to be a marker of metastatic potential in some breast cancers." (PMID 34493070, 2021). "This suggests that the reversion of the oncogenic RhoC-mediated phenotype in breast cancer may be mediated by RhoB, and that RhoB and RhoC may have antagonistic roles in TNBC cell lines." (PMID 32992837, 2020). "Therefore, we next applied our imaging and analysis strategy to explore the potential for fragmented mitochondria in breast cancer cells that lack either the Rho-like family of Rho-GTPases RhoA or RhoC via CRISPR/Cas9 knockout (WT, RhoA KO, RhoC KO)." (PMID 32472013, 2020). "Since ALDH has been shown to confer cellular resistance to a variety of cytotoxic drugs used for breast cancer, such as cyclophosphamide and its active derivative, doxorubicin and cisplatin, this offers a potential mechanism for how RhoC mediates chemoresistance in breast cancer cells." (PMID 32992837, 2020). "Application of the MitoTracker strategy downstream of the metabolic flux assay revealed that RhoC deletion increases the number of fragmented mitochondria in inflammatory breast cancer cells, which we hypothesize contributes to the depleted OCR levels." (PMID 32472013, 2020). "It has been ascertained that RhoC affects response to chemotherapy in the breast cancer model." (PMID 31488179, 2019). "To test the role of RhoA and RhoC in M2a-induced breast cancer cell migration, we stimulated MDA-231 or SUM-149 wild type (WT), RhoA CRISPR-Cas9 knockout (ΔRhoA), or RhoC CRISPR-Cas9 knockout (ΔRhoC) with either base media or M2a conditioned media and monitored wound closure over 24 h." (PMID 31214501, 2019). "Therefore, it is possible that ethanol activates ROS-p38γ-RhoC pathway which results in enhanced aggressiveness of breast cancer." (PMID 26655092, 2016). "RhoC overexpression has been detected in many cancers such as gastric and breast cancer." (PMID 25649143, 2015). "RhoC was initially described to contribute to melanoma metastasis in mouse models, and has since been described to participate in cancer spreading in other types of cancer such as prostate and breast cancer." (PMID 25677806, 2015). "RhoC and fibronectin have been implicated in IBC signaling and breast cancer cell migration." (PMID 24039951, 2013). "Moreover, RhoC knockout selectively inhibits metastasis–independent from primary tumor formation–in a transgenic breast cancer model." (PMID 22911725, 2012). "Additionally, we have demonstrated that RhoC hyperactivation drives breast cancer cell dormancy, potentially through JNK/SAPK." (PMID 22046561, 2011). "They found this miR to be highly expressed in metastatic breast cancer cells, and its overexpression initiated invasion and metastasis in a combination of mouse and human cell models by indirectly activating the pro-metastatic gene RhoC." (PMID 21047409, 2010). "Increased expression of RhoC correlates with progression and poor prognosis of ductal adenocarcinoma of pancreas, hepatocellular cancer, breast cancer, ovarian cancer, bladder cancer, gastric cancer, esophageal SCC, head and neck SCC, prostate cancer, and non-small cell lung carcinoma (NSCLC)." (PMID 20822528, 2010). "Besides playing a role in the metastasis of some human cancers, namely of breast carcinomas, overexpression of the RhoC protein was detected in glial precursors during differentiation of fetal neuroepithelial cells." (PMID 20459794, 2010). "The viral form of the three pRevTre-RhoC transgenes were used to transduce the breast cancer cells." (PMID 29147173, 2010). "MDA-MB-231 breast cancer cells were shown to express RhoC as demonstrated by RT-PCR." (PMID 29147173, 2010). "Some studies have proved that RhoC had a key role in metastasis of breast cancer." (PMID 17980029, 2007).
breast carcinoma (continued). "Studies have also demonstrated that, in addition to the Rac proteins, Rho proteins, especially RhoC, may contribute to breast cancer cell invasion." (PMID 16280046, 2005). "Also, while it is established that RhoC is relevant to breast cancer survival (via cell death inhibition) and progression (via the promotion of proliferation, invasion, and metastasis), data accumulated so far only reveals the relevance of RhoA to breast cancer cell progression." (PMID 40214422, 2025). "RhoC overexpression in BC was first identified in a clinical subtype known as Inflammatory Breast Cancer." (PMID 38807216, 2024). "In addition, we investigated whether RhoA and RhoC expression contributes to poor prognosis in patients with breast cancer." (PMID 33406809, 2021). "Indeed, treatment of MCF-7 breast cancer cells with the chemotherapeutic, etoposide, resulted in increased RhoC expression, and stable expression of a constitutively active RhoC resulted in the induction of an EMT-like phenotype characterized by a reduction of membrane-expressed E-cadherin." (PMID 32992837, 2020). "Using intravital imaging, Giampieri and group showed that TGF-β switches breast cancer cells from cohesive to single cell motility, which is essential for intravasation, by transcriptionally reprograming tumor cells, thereby leading to alteration in the expression of several genes, including RhoC." (PMID 31340863, 2019). "In addition, FAM53A may affect the migration and invasion of breast cancer cells by regulating the expression of RhoA, RhoB, RhoC, ROCK1, and MMP9." (PMID 31799197, 2019). "Therefore, we hypothesized that RhoC plays a regulatory role specifically in TAM-induced breast cancer cell migratory and invasive responses." (PMID 31214501, 2019). "The data indicate that RhoC may be more important for breast cancer development compared to RhoA." (PMID 29152087, 2017). "Interestingly, RhoC can induce the production of angiogenic factors in breast cancer, and this could help promote entry into blood vessels and thereby metastasis dissemination." (PMID 20822528, 2010). "Overexpression of wildtype RhoC in vitro drives invasion of HME and MCF10A cells in both 2D and 3D culture, and high levels of RhoC observed in the SUM149 inflammatory breast cancer cell line are thought to increase production of pro-angiogenic factors." (PMID 38807216, 2024). "In this study, we found a higher PSI value in breast cancer patients than in normal samples for COMMD4_AS2, GNAS, MATR3, RHOC and COMMD4_AS1, whereas the PSI value was lower for MARK3, POLDIP3 and FASTK." (PMID 36725888, 2023). "Mechanistically, TEM8 increases active RhoC level and induces ROCK1-mediated phosphorylation of SMAD5, in a cascade essential for promoting stemness and VM capacity of breast cancer cells." (PMID 34285210, 2021). "This study demonstrates that the RhoA or RhoC/YAP pathway accelerated tumor metastasis via increased expression of RHAMM and CXCR4 in melanoma and breast cancer cells." (PMID 33406809, 2021). "We demonstrate that CRISPR-Cas9 knockout of RhoC in SUM 149 and MDA 231 breast cancer cells results in increased normalization of junctional integrity denoted by junction protein expression/colocalization." (PMID 34513691, 2021). "Another reported mechanism that has been recently published is the role of one of the GTPases, known as RhoC GTPase, in reducing the gene expression of KAI1 in an invasive form of breast cancer." (PMID 34121877, 2021). "Lastly, transient degradation of RhoA and RhoC proteins by targeted siRNAs significantly reduced MDA-MB-231 TNBC cell growth in vitro and in mouse models of breast cancer." (PMID 32992837, 2020). "RhoC expression is positively correlated with the expression of ALDH, a breast cancer stem cell marker, and is a potential direct regulator of ALDH expression in breast cancer cells." (PMID 32992837, 2020).
breast carcinoma (continued). "With regard to breast cancer stemness, the expression of RhoC segregates with ALDH positivity and it impacts the frequency of CSCs found in a previous tissue microarray where 136 breast cancer tissues were analyzed." (PMID 31681564, 2019). "MyoGEF, a molecule responsible for activation of RhoA and RhoC was found to regulate both polarity and invasive phenotypes of MDA-MB-231 (an invasive breast cancer cell line)." (PMID 31340863, 2019). "In our previous work, we observed that conditioned media extracts from in vitro, unpolarized macrophages significantly enhance migration in inflammatory breast cancer cells (such as SUM-149 cells) and that this process is regulated by RhoC." (PMID 31214501, 2019). "These CDP/RhoC-siRNA complexes together form “smart” particles at a low N/P ratio of 2.5/1 which successfully escaped the endosomes due to DMAEMA, and almost completely suppressed the RhoC protein levels in SUM149 and MDA-MB-231 breast cancer cells." (PMID 34322587, 2017). "In breast cancer stem cell (BCSC), RhoC is an important regulator of BCSC metastasis and its expression is highly correlative with BCSC marker ALDH1." (PMID 27557508, 2016). "Previously, overexpression of RhoC protein has been detected in inflammatory breast cancer (IBC), an aggressive form of breast cancer that is highly infiltrative and metastatic with poor prognosis of patients." (PMID 23382905, 2013). "To extend our findings on the relationship between RhoC and BCSCs we used AQUA of immunofluorescence signals for RhoC and ALDH1 in cytokeratin-positive cells from a breast cancer tissue microarray." (PMID 22911725, 2012). "Clinically, expression of RhoC and the BCSC marker ALDH1 strongly correlate in patient breast cancer specimens." (PMID 22911725, 2012). "Conversely, experimental inhibition of PRDX6 expression decreased the invasive and potential potential of breast cancer cells, partially through regulation of uPAR, Ets-1, MMP-9, RhoC and TIMP-2 expression." (PMID 17980029, 2007). "Overexpression of peroxiredoxin 6 leads to a more invasive phenotype and metastatic potential in human breast cancer, at least in part, through regulation of the levels of uPAR, Ets-1, MMP-9, RhoC and TIMP-2 expression." (PMID 17980029, 2007). "All these results indicate that PRDX6 promotes breast cancer progression, partially through upregulation of uPAR, Ets-1, MMP-9 and RhoC expression and downregulation of TIMP-2 expression." (PMID 17980029, 2007). "Similarly, RhoA and RhoC knockdown by siRNA was also reported to reduce invasion, motility, and monolayer growth rate in SUM149 and MDA-MB-231 breast cancer cells." (PMID 40214422, 2025). "RhoC overexpression did not affect ERBB2 protein accumulation in transfected breast cancer cells in vitro." (PMID 38807216, 2024). "RhoC overexpression dramatically enhanced mammary tumor formation in FloxNeoNeuNT mice but showed a more subtle effect in the NIC line, which forms multiple mammary tumors after a very short latency." (PMID 38807216, 2024). "Additionally, miR-509 suppressed the trans-endothelial migration of breast cancer cells and contributed to the suppression of MMP9 via modulation of RhoC." (PMID 39175471, 2024). "Taken together, the AS events analyzed in COMMD4_AS2, EXOC7, RHOC, COMMD4_AS1 and POLDIP3 were related to a worse breast cancer prognosis, and could constitute potential prognosis biomarkers." (PMID 36725888, 2023). "Moreover, we confirmed that 4T1 cells, a highly metastatic mouse breast cancer cell line, expressed total and GTP-form RhoA and RhoC." (PMID 33406809, 2021). "RhoC activation can trigger the ROCK/Lin11/Isl1/Mec3 kinase (LIMK) pathway to phosphorylate and inactivate cofilin, thereby regulating the actin cytoskeleton to regulate human glioma, squamous cell carcinoma, and breast cancer cell migration." (PMID 34627249, 2021).
breast carcinoma (continued). "The expression of HOTAIR, an lncRNA known to be a negative prognostic marker, is under the influence of RhoC-ROCK signaling in breast cancer cells." (PMID 31340863, 2019). "The anti-tumor effect following cytofectin-mediated delivery of anti-RhoA and anti-RhoC siRNAs was evaluated in a breast cancer mouse model, developed by employing 4 × 106 of MDA-MB-231 cells (human breast carcinoma cells) into female athymic nude mice of 6 weeks of age." (PMID 29861465, 2018). "It is well established that in breast cancer, miR-10b suppress migration and invasion property by directly targeting HOXD10 and RHOC.It has been known that miR-10b also interacts with KLF4 to stimulate migration and invasion potential in esophageal squamous cell carcinoma." (PMID 27467502, 2016). "UBE2C expression was associated with that of the selected metastasis-related genes VEGF, CXCL-4, CCL5, NEDD9 and RHoC, in MCF-7 cells, so UBE2C may be involved in breast cancer metastasis." (PMID 24699941, 2014). "We observed that the AS events for COMMD4_AS2, GNAS, MATR3,COMMD4_AS1 and RHOC displayed a significant higher PSI value in cancer patients than in normal samples, while the PSI values were significantly lower for MARK3, POLDIP3 and FASTK in patients with breast cancer." (PMID 36725888, 2023). "Further studies are needed to validate these findings in other inflammatory and non-inflammatory breast cancer cell lines and to assess the mechanism of action by which RhoC expression may modulate STAT2 expression." (PMID 34513691, 2021). "However, since RhoC is predominantly upregulated in inflammatory breast cancer, COX-2 inhibitors may be especially useful in the treatment of specific breast cancer patients." (PMID 29152087, 2017). "Our results are in agreement with a similar study on RhoC expression in breast cancer cell lines, where ALDH positive cells exhibited a higher RhoC expression compared to non-ALDH expressing cells." (PMID 24533098, 2014). "To examine whether here too, miR-10b affects c-Jun expression through RhoC and NF1, we measured their expression levels in metastatic and non-metastatic breast cancer cells." (PMID 27494896, 2016). "Thus, cells with increased STAT2 and pSTAT2 upon stimulation with IFN-α were more resistant to IFN-α-driven transwell invasion inhibition, and furthermore RhoC expression affects STAT2 and pSTAT2 expression in different ways in inflammatory and non-inflammatory breast cancer cells." (PMID 34513691, 2021).
melanoma (34 papers, 2002 to 2026). A malignant, usually aggressive tumor composed of atypical, neoplastic melanocytes. "RhoA and RhoC have been strongly implicated in the aggressiveness and metastasis of a number of cancer types, including breast, prostate, and melanoma, but the precise mechanisms underlying those effects are not clear." (PMID 27600078, 2016). "Associations of RhoC expression with lymphatic metastases and poor survival has been confirmed in melanoma." (PMID 25823820, 2015). "Further studies are required to understand the mechanism of RhoC increase, as this gene has been implicated as an independent mitogen from RhoA, and can induce metastasis in melanoma cells." (PMID 25188245, 2014). "For example, high expression of RhoC is associated with increased invasion in breast, melanoma, pancreatic, bladder, hepatocellular, and non–small-cell lung carcinoma primary tumors or cell lines." (PMID 23977139, 2013). "Genomic comparison of melanoma variants suggested that proteins regulating actin organisation, such as RhoC, were overexpressed in highly metastatic melanoma cells." (PMID 19953094, 2010). "In addition, RhoC is associated with cancer invasion in melanoma, IBC and ovarian cancer." (PMID 23382905, 2013). "Pseudotime trajectory analysis identified critical genes (CYR61, JUN, RHOC) involved in melanoma cell state transitions." (PMID 41993933, 2026). "The human melanoma cell line FM3 naturally expresses high levels of the RhoC protein and of HLA-class II molecules." (PMID 40333248, 2025). "Inhibition of MRTF signaling in human melanoma suppressed RhoC-mediated lung metastases and enhanced in vitro sensitivity to targeted therapies, behavior similar to our results here." (PMID 37762086, 2023). "RhoA, RhoC, and Rac1 regulate cell cytoskeleton and gene transcription and are known to enhance melanoma migration, metastasis, and drug resistance." (PMID 37762086, 2023). "For instance, overexpression of the small GTPase RHOC has been reported to accelerate melanoma progression via mechanisms that regulate PI3K/AKT and ROCK signaling pathways." (PMID 35562405, 2022). "In melanoma patients, RhoC expression has been involved with the presence of lymphatic metastasis at the time of diagnosis and shorter disease-free and overall survival rates." (PMID 33406809, 2021). "Rho GTPases are overexpressed in cancer; particularly RhoC is a driver of melanoma metastasis by increased expression." (PMID 31935375, 2020). "We used a siRNA strategy to reduce RhoA, RhoB, or RhoC expression in CD70+ LB1319-MEL human melanoma cells." (PMID 26828592, 2016). "Other researchers demonstrated that RhoA and RhoC were also over-expressed in highly metastatic melanoma cells." (PMID 25671570, 2015). "Increase in RhoC gene expression is intriguing, because it was reported to promote tumor metastasis in melanoma." (PMID 25188245, 2014). "Increased expression of RhoC in metastatic melanoma cells in comparison with the poorly metastatic counterparts was the advent of studies implicating RhoC in carcinoma progression especially metastasis." (PMID 19953094, 2010). "Genomic analyses of metastatic melanoma cells have shown overexpression of RhoC protein, indicating an important role of the protein in tumour invasion." (PMID 19367286, 2009). "One study demonstrated that over expression of RhoC in a radial growth phase melanoma cell line, WM35, promoted cell invasion and increased signaling through the PI-3K/Akt pathway, independent of signaling through the RhoA downstream effector ROCK." (PMID 19400942, 2009). "For selecting the cell lines, we checked on the expression of three known molecular markers of melanoma progression, KISS1 and RHOC mRNAs and the αvβ3 integrin, in the panel of melanoma cell lines used here." (PMID 18211678, 2008). "The RHOC mRNA was detected in all melanoma cell lines, presenting an elevated expression particularly in the RGP cell line WM1789." (PMID 18211678, 2008).